CD36 (CD36 molecule (CD36 blood group))
Diseases named in the same sentence as CD36 in open-access papers (continued):
Sharing a sentence is not in itself a finding about the gene and the disease.
cancer (426 papers, 2001 to 2026). A tumor composed of atypical neoplastic, often pleomorphic cells that invade other tissues. "In vivo, PA promoted lymph node metastasis in orthotopic tumors comprising OSCC cells and CAFs, an effect abolished by CD36 knockdown in cancer-associated fibroblasts (CAFs)." (PMID 42227941, 2026). "Elevated levels of lipid transporters like CD36 are associated with a greater capacity for metastasis, emphasizing the crucial role of lipid absorption in supporting the spread of cancer cells." (PMID 40487761, 2025). "Our findings demonstrate a significant positive association between CD36 and various immune features, underscoring its immune-regulatory role across pan-cancers." (PMID 41550652, 2025). "Evaluation of CD36 correlation and association in different cancers with immunogenicity and prognosis is the aim of this study." (PMID 41550652, 2025). "CD36 deficiency in mouse prostate tissue can inhibit cancer uptake of fatty acid organisms and decrease tumorigenesis." (PMID 40956032, 2025). "A key finding of our study is the heterogeneous expression of CD36 across pan-cancers and its cancer-type-dependent clinical associations." (PMID 41550652, 2025). "Recent studies have shown that cancer-associated fibroblasts (CAFs) influence the metabolic activity of MDSCs through CD36 and the secretion of macrophage migration inhibitory factor (MIF), further exacerbating immune evasion." (PMID 40901479, 2025). "For each cancer type, the 95% CIs for AUC values are non-overlapping, supporting robust diagnostic performance of CD36 expression across these cancers." (PMID 41550652, 2025). "We noticed sufficient CD36 mutation counts in different cancers such as gain or missense, shallow and deep deletions, and amplification." (PMID 41550652, 2025). "CD36 in cancer-associated fibroblasts provides an immune-suppressive microenvironment by inhibiting migration factors, thus promoting the progression of HCC." (PMID 39774047, 2025). "GSEA analysis revealed cancer-type-dependent association of CD36 with hallmark pathways, whereas multiple cancer types showed positive correlation with immune and inflammation-related pathways and negative correlation with cell cycle-related pathways." (PMID 41550652, 2025). "In summary, medium-chain fatty acids are capable of selectively sensitizing cancer cells to the ferroptosis that is mechanically associated with the induction of fatty acid transporter CD36 and lipid peroxidation related enzyme ACSL4." (PMID 40077664, 2025). "CD36, a fatty acid scavenger receptor expressed in tumors, is associated with a poor prognosis in several cancers." (PMID 41465497, 2025). "High CD36 expression is linked to increased invasiveness and metastatic potential in several cancers, including breast, ovarian, prostate, and colorectal cancers." (PMID 40723225, 2025). "CD36-induced metastasis is known to be linked to the glucose and lipid metabolism of cancer cells and mediated through the GSK-3β/β-catenin signaling pathway." (PMID 39752516, 2025). "Increased FAs uptake mediated by CD36 is associated with PCa invasiveness, and silencing CD36 in PCa cells can reduce cell proliferation and decrease cancer severity." (PMID 41421797, 2025). "CD36, a scavenger receptor implicated in fatty acid metabolism and angiogenesis, has been extensively investigated in the context of cancer." (PMID 40565366, 2025). "Immune infiltration analysis of CD36 in pan-cancers revealed strong positive association with multiple immune cells such as macrophages, monocytes, DCs, NKs, and B cells, evaluated by using various algorithms." (PMID 41550652, 2025). "ROC curve analysis demonstrated strong diagnostic performance of CD36 expression across multiple cancer types, with AUC values exceeding 0.7 for each cancer type." (PMID 41550652, 2025).
cancer (continued). "Although CD36 has a context-dependent role, its differential expression across pan-cancer types suggests diagnostic and prognostic significance, aiding in patient stratification and the prediction of treatment outcomes." (PMID 41550652, 2025). "Taken together, these results indicate that CD36 levels are positively associated with cancer development." (PMID 38319449, 2024). "Blocking FASN was associated with increased CD36 expression, ensuring the cellular availability of fatty acids to sustain cancer cell proliferation." (PMID 39339236, 2024). "CD36 is also associated with cancer stem cells (CSCs), promoting CSCs proliferation, and maintaining stemness." (PMID 39627379, 2024). "CD36, a protein involved in fatty acid metabolism, is upregulated in cancer and associated with LN metastases." (PMID 39062552, 2024). "Emerging clinical evidence has shown that high levels of CD36 or its associated signature are correlated with malignancy and poor prognosis in several cancers." (PMID 39624081, 2024). "CD36, a fatty acid receptor, is closely associated with metabolism-related diseases, including cardiovascular disease and cancer." (PMID 38319449, 2024). "CD36 is known as a bad prognostic marker in cancer, and it is also associated with adverse clinicopathological features in many cancers." (PMID 39062552, 2024). "CD36 has recently been implicated in the development of resistance to several distinct classes of therapies in cancer." (PMID 37371076, 2023). "When using FASNi, there is a compensatory effect caused by CD36 upregulation, which desensitizes FASNi’s action to halt cancer cells from obtaining FA for cell proliferation." (PMID 36675817, 2023). "Studies have also shown that CD36 expression is highly associated with EMT gene signatures across multiple cancer types." (PMID 37371076, 2023). "CD36 also plays a role in lipid metabolism of cancer associated T-cells leading to impaired cytotoxic CD8+ T-cell and enhanced Treg cell function." (PMID 37226083, 2023). "Ox-LDL binds to lectin like oxidized low-density lipoprotein receptor-1 (LOX-1) and Cluster Differentiating 36 (CD36), inducing mutations, leading to inflammation, cell proliferation, and cancer metastasis." (PMID 37305043, 2023). "Data from the TCGA database also indicates that CD36 is amplified and mutated in a variety of cancer types." (PMID 37371076, 2023). "Many studies have implicated CD36-mediated FA uptake activity as its main mechanism of action in cancer cells." (PMID 37371076, 2023). "Several recent studies have implicated CD36 in facilitating cancer cell metastasis in a wide variety of cancer types." (PMID 37371076, 2023). "Multiple studies have shown that CD36 is enriched in cancer stem cell (CSC) populations from several cancer types, and its expression is often associated with an enhanced metastatic capacity." (PMID 37371076, 2023). "CD36 is negatively linked to the prognosis of patients and is an important biomarker of malignant tumors." (PMID 37056351, 2023). "We show that the ectopic addition of each of the three ligands to cancer-associated fibroblasts (CAFs) elevates the expression of CD36, as well as the adipogenic marker FABP4." (PMID 36361532, 2022). "Gene set enrichment analysis shows an enrichment of genes involving focal adhesion, gap junction and cancer-associated pathways in HT29 p-Lenti-CD36 overexpression cell line as compared to the HT29 p-Lenti-Control." (PMID 35008415, 2022). "We have also demonstrated that high expression of CD36 is associated with cancer cells that are prone to metastasis." (PMID 35008415, 2022). "Ox-LDL binds to the lectin-like oxidized low-density lipoprotein receptor-1 (LOX-1) and cluster of differentiation 36 (CD36) to induce mutations, resulting in inflammation, cell proliferation, and metastasis of cancer." (PMID 35251975, 2022).
cancer (continued). "For example, normal cells recruited into the TME (adipocytes, cancer associated fibroblast, macrophages) can be the source of FA that activate CD36 in cancer cells." (PMID 36568966, 2022). "Based on this evidence, further studies must be investigated to understand the underlying mechanism and association of BPA with CD36 in cancer progression and immune response." (PMID 36428985, 2022). "The reason for this potent anti-cancer effect in CD36 inhibition is linked to inactivation of Wnt/Beta-catenin, a major driver of oncogenic cell growth in cancer cells." (PMID 35634242, 2022). "Aside from its role in transporting fatty acids into cells, CD36 has been implicated in a myriad of roles that enhance cancer cell growth, metastasis, and EMT." (PMID 35163079, 2022). "Fatty acid-binding protein 4 (FABP4) was found to facilitate the transfer of adipocyte-derived FAs between cancer-associated adipocytes and cancer cells, while CD36 facilitates FA uptake, thus providing tumours with sufficient energy to grow and progress." (PMID 35328822, 2022). "CD36 has also been implicated in some metabolic diseases, such as diabetes, Alzheimer’s disease, and cancer." (PMID 35216285, 2022). "Inhibition and knockdown of CD36 have deleterious effects on cellular proliferation in many cancers, rendering CD36 a diagnostic biomarker and a potential target for therapy." (PMID 35634242, 2022). "Conversely, CD36 is often overexpressed in cancer (epithelial) cells and associated with worse clinical outcomes." (PMID 36361532, 2022). "The understanding of the FA uptake role of CD36 in the progression of these cancers has been greatly substantiated by loss-of-function studies and adipocyte co-culturing." (PMID 35448537, 2022). "For example, in a healthy mammary gland, fibroblasts (FBs) overexpress CD36; and the downregulation of CD36 is one of the hallmarks of cancer-associated FBs." (PMID 34572749, 2021). "Univariate Cox analysis was used to evaluate the association of CD36 expression with overall survival among 33 types of cancer." (PMID 34234847, 2021). "For example, prostate-specific deletion of SR-B2/CD36 of cancer-susceptible Pten−/− mice slowed cancer progression, while SR-B2/CD36 antibody therapy reduced cancer severity in patient-derived xenografts." (PMID 33413672, 2021). "CD36 is frequently acquired or amplified in CSCs of many cancer types, which is also associated with more aggressive tumor and poorer prognosis." (PMID 34603046, 2021). "CD36 was overexpressed on the cell membrane of several cancer cells and was associated with the aggressive behaviours of these cancers, including oesophageal and gastric cancer, breast cancer, cervical cancer, and renal cancer." (PMID 34722305, 2021). "In GBM, CD36 is expressed in tumorigenic cancer stem cells, and is associated with a pro-invasion phenotype." (PMID 34277624, 2021). "Continuation of this work of dissecting the details of the underlying molecular mechanisms and testing the role of CD36 in mobilizing other types of lipids will outline new directions for intervention in metabolic disease and cancer." (PMID 34314388, 2021). "Despite this quantitatively “minor” role in fatty acid uptake, recent loss-of-function studies have clearly shown that SR-B2/CD36 is critical in prostate, ovarian, oral, cervical, gastric, breast, and liver cancer biology." (PMID 33413672, 2021). "CD36 is involved in FA uptake, clearance of apoptotic cells, and angiogenesis and it has been implicated in several diseases, including cancer." (PMID 34386430, 2021). "As to the genes reported to positively relate to the efficacy of ICIs, CD36 expression was positively correlated with most of them but negatively associated with a small proportion of cancer type-specific patterns." (PMID 34234847, 2021). "CD36 has been known to be associated with altered lipid metabolism and initiation of metastasis, contributing to cancer progression." (PMID 34257543, 2021).
cancer (continued). "The function of CD36 in fatty acid metabolism is well documented and several studies have revealed its association with cancer." (PMID 33771982, 2021). "Another carcinogenic modulator, CD36, is a membrane glycoprotein that is associated with elevated fatty acids absorption to modulate cancer progression and metastasis in various cancers such as ovarian, cervical, liver, and stomach." (PMID 34887764, 2021). "CD36 overexpression is associated with the poor prognosis and resistance of cancer cells into chemotherapy-mediated apoptosis." (PMID 32380783, 2020). "We demonstrate that a decrease in FASN expression is associated with selective induction of CD36 and that this phenomenon is consistent among multiple cancer models." (PMID 32850342, 2020). "It has been shown that, in some forms of cancer, such as colon, breast, and ovarian, a low-CD36 expression in the primary tumor is associated with higher metastasis grade and poor prognosis." (PMID 32781778, 2020). "Our findings that CD36 is required for lipid uptake and cell migration in REDD1-deficient cells provide new insight into CD36 activation in cancer, and they collectively suggest a direct contribution of CD36 to the pathogenesis of REDD1-deficient tumors." (PMID 32273287, 2020). "CD36 not only uptakes of free fatty acids and cholesterol, and the transfer of intracellular signals, but also pertains to the cancer-associated antigen presentation, inflammation, and angiogenesis." (PMID 33194756, 2020). "CD36 has now been implicated as a mediator of poor outcomes and metastasis in multiple different cancers." (PMID 32273287, 2020). "Out of a study on more than 2500 cases of different cancers came the confirmation of a role of CD36 in metastasis by investigating genes implicated in metabolic reconnection to aerobic glycolysis and fatty acids synthesis in metastatic vs. primary tumors." (PMID 32781778, 2020). "CD36 is a multifunctional scavenger receptor and lipid transporter implicated in metabolic and inflammatory pathologies, as well as cancer progression." (PMID 31035848, 2019). "Intriguingly, blockade of CD36 in OSCC cells also causes severe intercellular lipid accumulation in cancer cells, which leads to lipotoxic cell death and impaired metastasis." (PMID 31410189, 2019). "Unlike its well-known and better-studied binding partners (thrombospondins (TSPs) 1 and 2) but with controversial involvement in cancer progression, CD36 is increasingly emerging as a prognostic marker associated with the metastatic process." (PMID 30069479, 2018). "This decrease in CD36 is particularly significant, because a similar downregulation of CD36 gene expression is observed in carcinoma-associated fibroblasts (CAFs) compared to fibroblasts from reduction mammoplasty (RMF)." (PMID 29651637, 2018). "We hypothesized that the increased sensitivity of cancer cells to ferroptosis by LA-m might be associated with its upregulating effect on CD36 expression." (PMID 40077664, 2025). "For instance, CD36 has been associated with the metabolism of fatty acids and the spread of tumors, with its expression levels linked to unfavorable outcomes in various types of cancer." (PMID 40061897, 2025). "Additionally, some new subtypes of CAFs have been identified in HCC, namely vascular cancer associated fibroblasts (vCAFs), mesenchymal cancer associated fibroblasts (mCAFs), lipid processing cancer associated fibroblasts (lpCAFs), apCAFs and CD36+ CAFs." (PMID 40248695, 2025). "CD36 showed positive correlations with immune and inflammatory pathways but negative associations with proliferative and cell cycle-related pathways across multiple cancer types." (PMID 41550652, 2025).
cancer (continued). "Additionally, there are several aME genes whose dysregulation is associated with cancers when misregulated, such as Mmp14, Nid1, Mdm2, Cd36, and Id3." (PMID 41223055, 2025). "Furthermore, Ox-LDL receptors such as LOX-1 and CD36, along with associated downstream signaling cascades, play an important role in cancer progression." (PMID 39290325, 2024). "Research in cancer cells revealed a positive association between CD36 and AKT, suggesting that CAVPENET inhibition of AKT might be responsible for reducing the availability of fatty acids in PCa cells, via distinct mechanisms." (PMID 39339236, 2024). "High levels of either CD36 or CD47 are associated with poor outcomes for cancer patients." (PMID 39627379, 2024). "CD36 is also implicated in the etiology of drug resistance mechanisms to a broad range of drug classes in cancer cells via both FA metabolism-dependent and -independent fashions, further adding complexity to the role of CD36 in cancer biology." (PMID 37371076, 2023). "Similarly, lipid accumulation in NK cells caused by high CD36 expression levels, also attenuates the toxic effects on cancer cells." (PMID 37545500, 2023). "Importantly, CD36 is linked to metabolic crosstalk between cancer cells and their microenvironment and drives the tumor cell’s dependence on exogenous lipids." (PMID 35163079, 2022). "However, low CD36 expression was marginally associated with poorer prognosis in two types of cancer (KIRC HR =0.99, 95% CI = 0.99 to 1.00, P = 0.004; PAAD HR = 0.97, 95% CI = 0.95 to 1.00, P = 0.032)." (PMID 34234847, 2021). "High CD36 expression was marginally associated with poorer prognosis in four types of cancer (COAD HR = 1.02, 95% CI = 1.01 to 1.04, P = 0.007; ESCA HR = 1.02, 95% CI = 1.01 to 1.03, P = 0.004; READ HR = 1.07, 95%CI = 1.00 to 1.14, P = 0.046; STAD HR = 1.02, 95%CI = 1.00 to 1.03, P = 0.017)." (PMID 34234847, 2021). "However, the inhibition of CD36 caused a decrease in fatty acid intake of cancer cells and reduced the accumulation of cholesterol and lipid droplets and the intracellular reactive oxygen species (ROS) in cancer cells." (PMID 33194756, 2020). "By associating with different ligands, CD36 is involved in cancer development." (PMID 32781778, 2020). "Therefore, the preferential uptake of D-bLP in TAM or CAF over 4T1 cancer cells would be associated with the highly expressed SR-BI and its synergistic effects with CD36." (PMID 31346166, 2019). "CD36 has been implicated in contributing to cancer progression." (PMID 25866768, 2015). "In addition, 49 genes have been reported to be relevant to immune diseases, such as CXCL12, COL1A1, MMP9, and CD36, likely reflecting an inflammatory–type response often associated with cancer." (PMID 21060876, 2010). "Mechanically, cancer cells acquired exogenous fatty acids released by cancer-associated adipocytes through cell surface fatty acid translocase such as CD36, and then stored excessive energy as lipid droplets that could be further broken down into free fatty acids entering fatty acid oxidation." (PMID 38693136, 2024). "Moreover, it has also been demonstrated that CD36 is expressed by immunosuppressive cells, such as regulatory T cells (Tregs) and myeloid-derived suppressor cells (MDSCs), and is associated with immunosuppression in cancer." (PMID 39273384, 2024). "In addition to de novo lipid synthesis, cancer cells can also increase FA uptake from the extracellular interstitium through several plasma membrane proteins, including the LDL receptor and the FA translocase CD36, whose upregulation associates with poor prognosis in several types of cancers." (PMID 37561190, 2023). "CD36-mediated intracellular signals could be initiated by the physical association of the Src protein tyrosine kinase, which is regarded as an oncogene in the development of cancer." (PMID 33771982, 2021).